UTP20 (UTP20 small subunit processome component)
Description:
Part of the small subunit (SSU) processome, first precursor of the small eukaryotic ribosomal subunit. During the assembly of the SSU processome in the nucleolus, many ribosome biogenesis factors, an RNA chaperone and ribosomal proteins associate with the nascent pre-rRNA and work in concert to generate RNA folding, modifications, rearrangements and cleavage as well as targeted degradation of pre-ribosomal RNA by the RNA exosome. Involved in 18S pre-rRNA processing. Associates with U3 snoRNA.
Synonyms: DRIM; 1A6/DRIM
Tractability: Small molecule: a structure with a bound ligand is known. Antibody: its Gene Ontology location is reachable by antibodies, with high confidence. PROTAC: ubiquitination databases record sites on it; its protein half-life has been measured.
Gene: Protein-coding gene on chromosome 12 (101,280,105 to 101,386,618, forward strand). Ensembl gene ENSG00000120800.
Subcellular location: Nucleus, nucleolus
Subcellular location (Human Protein Atlas): Nucleoli; Plasma membrane
Pathways (Reactome):
Metabolism of RNA: Major pathway of rRNA processing in the nucleolus and cytosol; rRNA modification in the nucleus and cytosol
Gene Ontology:
Molecular function: protein binding; RNA binding
Biological process: ribosomal small subunit biogenesis; rRNA processing; endonucleolytic cleavage in 5'-ETS of tricistronic rRNA transcript (SSU-rRNA, 5.8S rRNA, LSU-rRNA); endonucleolytic cleavage in ITS1 to separate SSU-rRNA from 5.8S rRNA and LSU-rRNA from tricistronic rRNA transcript (SSU-rRNA, 5.8S rRNA, LSU-rRNA); endonucleolytic cleavage to generate mature 5'-end of SSU-rRNA from (SSU-rRNA, 5.8S rRNA, LSU-rRNA); maturation of SSU-rRNA; negative regulation of cell population proliferation
Cellular component: nucleolus; small-subunit processome; 90S preribosome; cytoplasm; nucleoplasm; preribosome, small subunit precursor
Genetic constraint (gnomAD): Loss-of-function variants: 137 observed, 289.63 expected, observed/expected ratio (o/e) 0.47, 90% interval 0.41 to 0.55. The upper end of that interval is the gene's LOEUF score, 0.55, which puts it in group 2 of 6, group 1 being the genes least tolerant of losing a copy. Missense variants: 2,728 observed, 3,061.4 expected, observed/expected ratio (o/e) 0.89, 90% interval 0.86 to 0.92. Synonymous variants: 1,046 observed, 1,096.3 expected, observed/expected ratio (o/e) 0.95, 90% interval 0.91 to 1.
Homologues: Orthologues: chimpanzee UTP20 (99% identical), macaque UTP20 (97% identical), pig UTP20 (91% identical), rabbit UTP20 (90% identical), dog UTP20 (90% identical), mouse Utp20 (86% identical), rat Utp20 (86% identical), guinea pig UTP20 (79% identical), tropical clawed frog utp20 (64% identical), zebrafish utp20 (57% identical), Drosophila melanogaster CG4554 (26% identical), Caenorhabditis elegans utp-20 (23% identical).
Diseases named in the same sentence as UTP20 in open-access papers:
UTP20 is named in the same sentence as 8 diseases in open-access papers, as found by Europe PMC text mining. Sharing a sentence is not in itself a finding about the gene and the disease. The quoted sentences say what the papers report.
breast carcinoma (1 paper, 2020). "PE‐Lap (FBP1, ITGA11, TRIM68, BCAT1, ZNF780A, UTP20 and GRB7) predicted outcomes of breast cancer patients treated with lapatinib." (PMID 34766125, 2020).
colorectal cancer (1 paper, 2024). A primary or metastatic malignant neoplasm that affects the colon or rectum. "Furthermore, the Utp20 gene has been identified as also being associated with colorectal cancer." (PMID 38339272, 2024).
coronary artery calcification (1 paper, 2015). Calcification of the coronary artery, used as a measure of coronary atherosclerosis, a risk factor for myocardial infarction. "Additionally, an intronic SNP in UTP20 was associated with coronary artery calcification in the Framingham Heart Study (P = 7.0 × 10-6)." (PMID 25689165, 2015).
jaw cysts (1 paper, 2026). "The identified 6 proteins, namely CD79A, CD5, KRR1, UTP20, AATF, and WDR43 - may be closely associated with the pathogenesis of jaw cysts." (PMID 42175431, 2026). "UTP20, AATF, and CD5 may represent potential candidate biomarkers associated with jaw cysts." (PMID 42175431, 2026).
tumor (1 paper, 2023). "Interestingly, the structural avidity of UTP20-specific TCRs correlated with their frequency in the tumor compartment, and was the highest for clonotype 5, indicating that tumor-resident clones have higher structural avidity." (PMID 37280206, 2023).
UTP20 also shares sentences with these, for which no sentence is quoted: alcohol dependence (1 paper); cancer (1); infection (1).